APOE (apolipoprotein E)
Diseases named in the same sentence as APOE in open-access papers (continued):
Sharing a sentence is not in itself a finding about the gene and the disease.
atherosclerosis (continued). "In ApoE−/− mice, hBD3 inhibited atherosclerosis progression and suppressed P.gingivalis LPS-induced NF-κB activity." (PMID 36823573, 2023). "The observed plaque regression in TG/ApoE mice demonstrates the potential for therapeutic interventions targeting RhoA or macrophage polarization to halt or reverse atherosclerosis." (PMID 37628966, 2023). "The ApoE KO mice were placed on a high-fat diet over 12 weeks to accelerate atherosclerosis development." (PMID 36865232, 2023). "In an ApoE–/– mouse model with atherosclerosis, the higher absorption of FRb-targeted liposomes was observed in vivo." (PMID 37229223, 2023). "During the development of atherosclerosis in HFD-fed ApoE-knockout mice, monocytes can migrate to the subendothelial space of the intima; this process is mediated by VCAM-1." (PMID 37764856, 2023). "This molecule suppressed VSMC pyroptosis and atherosclerosis development in ApoE-/- mice fed a western diet." (PMID 37765019, 2023). "This, in turn, played a role in the beneficial effects against atherosclerosis observed in ApoE-knockout mice with hyperhomocysteinemia." (PMID 38074127, 2023). "Crossing apolipoprotein E knockout (apoE–/–) mice, an established model of atherosclerosis, with mice that express a hepcidin-resistant ferroportin mutant (Fpnwt/C326S) aggravated atherosclerosis via increased levels of NTBI and oxidative stress." (PMID 37299408, 2023). "APOE was reported to suppress atherosclerosis and has also other protective functions such as inhibition of platelet aggregation, anti-inflammatory effects and regulation of microRNA levels." (PMID 38084238, 2023). "For instance, a study investigating atherosclerosis in EC-lineage tracing ApoE knockout mice found that females exhibited less EndoMT at the advanced stages of atherosclerosis." (PMID 37649604, 2023). "GEO and citral treatment ameliorated atherosclerosis in ApoE−/− mice by suppressing meta-organismal metabolism of gut microbiota-host-derived TMA and TMAO and remodeling gut microbiota composition." (PMID 37210385, 2023). "The macrophage-targeted Plau overexpression has been shown to be deleterious in an apoE−/− mouse model of atherosclerosis." (PMID 37332345, 2023). "The number of circulating pro-inflammatory monocytes is significantly increased in animal models of atherosclerosis such as the ApoE−/− mouse, and pro-inflammatory cytokines are secreted during atherosclerotic lesion progression." (PMID 37628966, 2023). "APOE plays a central role in determining plasma levels of cholesterol and hyperlipidemia and has been investigated as a key determinant of atherosclerosis." (PMID 38034385, 2023). "In conclusion, CFI-400945 prevents carotid arterial neointima formation in C57BL/6 mice but accelerates atherosclerosis in ApoE−/− mice, likely through mitotic arrest and subsequent induction of polyploidization and apoptosis." (PMID 36750553, 2023). "Together, these data revealed that exercise alleviates atherosclerosis in ApoE-/- mice at least partially via EVs." (PMID 37191422, 2023). "PYR-41 inhibits the ubiquitin-activating enzyme UBA1 to alleviate atherosclerosis and suppress the inflammatory response of macrophage in ApoE-/- mice." (PMID 37244925, 2023). "Recent reports have demonstrated that the inhibition of JAK/STAT signaling alleviated atherosclerosis in both ApoE−/− mouse and rabbit atherosclerosis models." (PMID 37089432, 2023). "We investigated the effect of the intraperitoneal injection of FT-H on the progression of atherosclerosis in APOE-knockout mice (Apo-E(−/−) mice)." (PMID 37504565, 2023). "ANGPTL8 knockout significantly inhibited the progression of AAA and atherosclerosis in ApoE−/− mice." (PMID 37294581, 2023). "Another study demonstrated an association between cell death and oxidative stress-associated DNA damage and PARP activation within atherosclerotic plaques in apolipoprotein E [ApoE] (−/−) model of high-fat diet-induced atherosclerosis." (PMID 36829935, 2023).
atherosclerosis (continued). "We also demonstrated that selective deletion of myeloid-PTP1B prevents severe atherosclerosis in the ApoE(−/−) mouse model of atherosclerosis." (PMID 37828508, 2023). "Impaired phosphatidylcholine biosynthesis has been reported to reduce atherosclerosis in ApoE−/− mice." (PMID 36600244, 2023). "We previously demonstrated that kefir peptides (KPs) alleviated atherosclerosis in high-fat diet (HFD)-induced apolipoprotein E knockout (ApoE−/−) mice." (PMID 37091976, 2023). "Next, we took advantage of a standard rodent model of atherosclerosis consisting of the administration of a high-fat diet to ApoE−/− mice." (PMID 37989732, 2023). "In atherosclerotic arteries, XO’s activity is increased and is responsible for the production of O2− and H2O2; consequently, the use of XO inhibitors positively affects endothelial function and slows atherosclerosis progress in apoE-KO mice." (PMID 37371915, 2023). "TMAO promotes atherosclerosis in apolipoprotein E–KO (ApoE–/–) mice by inducing EC pyroptosis and activates NLRP3 inflammasome." (PMID 36394956, 2023). "Resveratrol and Tribulus terrestris L. extract ameliorates atherosclerosis by inhibition of vascular smooth muscle cell proliferation in ApoE−/− mice via suppression of ERK signaling pathway." (PMID 37021059, 2023). "Overexpression of DNMT1 in macrophages significantly increases pro-inflammatory cytokine production and accelerates atherosclerosis in ApoE KO mice." (PMID 37947606, 2023). "In general, the evidence from this study suggests that oridonin has a protective effect on the development of atherosclerosis in ApoE−/− mice." (PMID 37155118, 2023). "In ApoE−/− mice, Dnmt3b silencing attenuated atherosclerosis by decreasing lesion size and macrophage content while increasing collagen and smooth muscle cell content." (PMID 38031118, 2023). "Fer-1, a widely used ferroptosis inhibitor, was reported to present anti-atherosclerosis through attenuating lipid peroxidation and endothelial dysfunction in ApoE-/- mice 27, which can be also confirmed in our present work." (PMID 37771765, 2023). "To investigate the impact of DSBs accumulation on atherosclerosis, we generated Ku80+/− ApoE−/− mice and fed them a high-fat diet for 4 weeks, starting from 60 days of age." (PMID 37777633, 2023). "The CUMS-induced atherosclerosis model was developed in Western diet-fed apolipoprotein E (ApoE)-/- mice." (PMID 37692113, 2023). "Atherosclerotic lesion area in the aortic arch of apoE−/− mice was 5.9 ± 1.2%; CETP expression significantly increased atherosclerosis in apoE−/− mice (13.1 ± 2.2%)." (PMID 37004910, 2023). "Male C57BL/6 ApoE−/− mice were fed a high-fat and high-choline diet to induce atherosclerosis and were subjected to in vivo studies." (PMID 37322486, 2023). "In parallel, dapagliflozin treatment decreased circulating levels of NLRP3, IL-1β, and IL-18, as well as in the abdominal aorta of ApoE−/− mice with DM and atherosclerosis." (PMID 37175496, 2023). "ApoE deficiency and abnormalities cause hyperlipoproteinemia type III, which is characterized by early atherosclerosis and cholesterol accumulation in the blood." (PMID 37396111, 2023). "Knocking out ApoE in mice with HFD-induced cardiovascular dysfunction can accelerate the progression of atherosclerosis." (PMID 37764856, 2023). "Studies confirm the anti-atherogenic function of macrophage-derived ApoE, indicating its critical role in lipid homeostasis and atherosclerosis management." (PMID 38066772, 2023). "In the ApoE−/− mice model, OPG knock-out was associated with an increased development of atherosclerosis." (PMID 37388640, 2023).
atherosclerosis (continued). "In a previous study, we identified a compound E1231 as a novel SIRT1 activator and demonstrated that it improved lipid and cholesterol metabolism in hyperlipidemic golden hamsters and an Apolipoprotein E knockout (ApoE−/−) mouse model of atherosclerosis." (PMID 37367070, 2023). "The only difference was in the levels of apolipoprotein E (ApoE), which prevents the development of atherosclerosis." (PMID 37998729, 2023). "To examine the preventive impact of SFN on atherosclerosis development, we fed ApoE−/− mice a high-fat diet for 16 weeks, during which the vehicle alone (Ctrl), 5 mg/kg SFN (SFN-L), or 15 mg/kg SFN (SFN-H) was administered every other day." (PMID 37432260, 2023). "We demonstrated thickening of the IMT, increased stiffness of the arterial wall combined with accelerated PWV, and reduced GRS in an ApoE−/−-based atherosclerosis model and in diseased aortic segments of AAA mice." (PMID 37894941, 2023). "According to a study, Tanshinone IIA downregulated the NF-κB activity, and reduced the expression of TNF-α and MCP-1, to stabilize vulnerable atherosclerosis plaque in ApoE−/− mice." (PMID 36823573, 2023). "Ang 1-7 was also found to attenuate atherosclerosis through a NO-mediated mechanism in apolipoprotein E knockout (ApoE-KO) mice." (PMID 37959338, 2023). "Together, these data demonstrated that inactivation of ApoE ameliorates HFD-induced obesity but facilitates lipid dys-homeostasis diseases such as atherosclerosis." (PMID 38062308, 2023). "Next, to confirm the effect of P. gingivalis infection on the development of atherosclerosis, ApoE−/− mice were orally infected with P. gingivalis for 12 weeks." (PMID 37380627, 2023). "Using Oil Red O staining, spontaneous atherosclerosis was compared in TG/ApoE−/− and control ApoE−/− mice at 10 to 60 weeks of age." (PMID 37628966, 2023). "Apolipoprotein E (apoE) is a secreted protein involved in lipid metabolism and in the development of Alzheimer’s disease and atherosclerosis." (PMID 37310025, 2023). "APOE-knockout mice (Apo-E(−/−) mice) are the most commonly used mouse model of atherosclerosis, with the presence of foam cells detectable at approximately 8 weeks and reaching an advanced stage of atherosclerosis after 20 weeks." (PMID 37504565, 2023). "This study showed that Robo4 expression was significantly decreased in the aorta of ApoE−/− mice with atherosclerosis induced by HFD feeding and that oral administration of RS significantly suppressed the decrease in Robo4 expression." (PMID 37998401, 2023). "Overexpression of GPX4 in ApoE−/− mice inhibited the progression of atherosclerosis by suppressing lipid peroxidation." (PMID 36771298, 2023). "Tie1 deletion is known to decrease atherosclerosis in ApoE−/− mice by reducing vascular inflammation." (PMID 37476204, 2023). "Thus, in HFD-fed ApoE-deficient mice, oral administration of RS ameliorated abnormal lipid metabolism and reduced vascular endothelial inflammation and hyperpermeability, macrophage infiltration and accumulation, and smooth muscle cell proliferation in the arteries leading to atherosclerosis." (PMID 37998401, 2023). "Mgl−/−/ApoE−/− mice showed improved atherosclerosis with increased plaque stability and reduced foam cell formation despite larger lesion size." (PMID 36834530, 2023). "Dynamin-related protein 1 (mdivi-1), a Drp1 specific inhibitor, alleviates atherosclerosis in ApoE−/− mice by suppressing mito-ROS/NLRP3-mediated M1 polarization." (PMID 38031118, 2023). "As a result, TG/ApoE−/− mice showed a more severe and earlier onset of atherosclerosis compared to the control ApoE−/− mice." (PMID 37628966, 2023). "In this research, we aimed to explore the influences of whole-grain highland barley on ameliorating atherosclerosis in ApoE−/− mice fed an HFD." (PMID 37836470, 2023). "Knockout of PTPN2 in apoE−/− mice leads to severe insulin resistance, and then leads to disordered lipid metabolism and atherosclerosis." (PMID 37670950, 2023).
atherosclerosis (continued). "The study also revealed that Trx2 expression reduced hypercholesterolemia-induced atherosclerosis by reducing ROS levels and improving NO bioavailability in Trx2 TG/ApoE−/− mice, resulting in significantly reduced lesions compared to ApoE−/− mice." (PMID 37507899, 2023). "The administration of teneligliptin, a DPP-4 inhibitor, attenuated atherosclerosis progression in apolipoprotein E (ApoE) knockout mice by alleviating inflammation and oxidative stress in both the vasculature and PVAT." (PMID 37627590, 2023). "UBA1 inhibitor PYR-41 can inhibit ox-LDL-induced proinflammatory cytokine expression, NADPH oxidases and lipid deposition in macrophage, thereby suppressing atherosclerosis in ApoE-/- mice with blunted proinflammatory responses in macrophage." (PMID 37244925, 2023). "Our previous study demonstrated a protective effect of dietary nitrate on the development of atherosclerosis in the apoE−/− mouse model." (PMID 36853380, 2023). "Inhibition of SAH hydrolase in ApoE−/− mice epigenetically up-regulates Drp1 expression through repressing DNA methylation in endothelial cells, leading to vascular senescence and atherosclerosis." (PMID 38031118, 2023). "To determine if this was the case in another commonly used model for atherosclerosis, we examined plaque formation in ApoE−/− mice and found it to be accelerated in this background too." (PMID 36894641, 2023). "Inhibition of Drp1 in apolipoprotein E (ApoE) knockout diabetic mice reduces endothelial dysfunction and atherosclerosis." (PMID 36860274, 2023). "Therapeutic strategies targeting lipid peroxidation using a free radical scavenger such as ferrostatin-1 alleviated atherosclerosis induced in ApoE-null mice fed a HFD." (PMID 37895313, 2023). "APOE is associated with increased carotid intima-media thickness (C-IMT), a marker of subclinical atherosclerosis which is independently associated with myocardial infarction and stroke." (PMID 38034385, 2023). "As apolipoprotein E (APOE) and paraoxonase 1 (PON1) were shown to suppress atherosclerosis, we investigated the associations of common functional PON1 and APOE polymorphisms with plasma lipid levels and the risk for late complications in T2D patients." (PMID 38084238, 2023). "While our manuscript was in preparation, two studies reported on atherosclerosis in adenine-treated apoE knockout mice." (PMID 36844738, 2023). "Th22 cells express IL-22 and have been found at increased levels in subjects with ACS, aggravating atherosclerosis on an ApoE−/− mice model further on by inducing Th17 proliferation." (PMID 37600028, 2023). "ApoE KO mice are a widely studied animal model, both as AD models as well as atherosclerosis models." (PMID 38075287, 2023). "Studies have shown that the expression of PTPN2 in monocytes is significantly downregulated in the apoE−/− inflammatory mouse atherosclerosis model." (PMID 37670950, 2023). "In an earlier study, transgenic expression of human CETP in 2- or 4-month-old apoE−/− mice (which naturally lack CETP) resulted in a moderate ∼2-fold increase in atherosclerosis." (PMID 37004910, 2023). "Reduced cholesterol efflux, reverse cholesterol transport and inhibited atherosclerosis progression in an ApoE-/- mouse model." (PMID 37275892, 2023).
atherosclerosis (continued). "In the current study we find that PF-06409577 reduces atherosclerosis in ApoE−/− and PCSK9 over-expression mouse models through a pathway requiring the AMPK β1 isoform." (PMID 38026185, 2023). "The aortic arch and thoracic aorta develop higher incidences of atherosclerosis but a relatively lower incidence of Ang II-induced aortic aneurysm than the abdominal aorta in the HFD-fed ApoE-KO plus Ang II infusion model." (PMID 37731512, 2023). "The sex-specific effects of chronic LD shifts on atherosclerosis in females and males cannot be attributed to cholesterol concentrations since in our experiment ApoE−/− males had higher concentrations of total and VLDL/LDL-cholesterol than females." (PMID 37064902, 2023). "By feeding a high-fat diet to 8-week-old apolipoprotein E knockout mice, an atherosclerosis model was created." (PMID 36537316, 2023). "ApoE−/− mice fed a Western diet for 4 months are commonly used as a mouse model of atherosclerosis, however, the plaques developed in this model are typically stable." (PMID 38328305, 2023). "In atherosclerotic coronary arteries, IL-1β levels were correlated with disease severity and knocking out IL-1β in atherosclerosis-prone ApoE−/− mice led to attenuation of disease development." (PMID 37251380, 2023). "In a recent report, overexpression of YAP and knock out of YAP in myeloid cells of ApoE KO mice increased and decreased atherosclerosis progression respectively, suggesting YAP as a therapeutic target of atherosclerosis." (PMID 37949969, 2023). "A hyperhomocysteinemia atherosclerotic model with ApoE−/− mice fed with a high-methionine diet was constructed to investigate the role of plasma homocysteine in atherosclerosis." (PMID 37308812, 2023). "It was shown that mice with a double knockout in the TRPA1 and apolipoprotein E (APOE) genes showed an increase in atherosclerosis plaques compared to mice with single knockout in the APOE gene after a high-fat diet treatment." (PMID 37326902, 2023). "Consistent with our results, another TRIM member, TRIM7, is increased in atherosclerosis, and interference of TRIM7 in the same high-fat diet ApoE-/- model effectively mitigated atherosclerosis progression in a recently reported study." (PMID 36229750, 2023). "APOE has been shown to play a detrimental role in atherosclerosis and vascular research—and ApoE−/− mice are the most frequently used pro-atherosclerotic animal model for various vascular diseases." (PMID 37509110, 2023). "Together, the results from our studies in ApoE-/- mice validated that lnc_000048 promoted atherosclerosis by activating the lnc_000048/MAP2K2/ERK axis." (PMID 36689133, 2023). "As expected, the expression of CETP increased atherosclerosis in apoE−/− mice (13.1 ± 2.2% compared with 5.9 ± 1.2% for ApoE−/− mice in the presence and absence of CETP expression, respectively; P = 0.005), confirming results from an earlier study." (PMID 37004910, 2023). "Our findings provide evidence of GSDME activation during the progression of atherosclerosis and confirm that the deficiency of GSDME exhibited significant effects on reducing atherogenesis and diminishing vascular inflammation in ApoE−/− mice." (PMID 37761020, 2023). "Drp1 inhibition was also found to reduce endothelial dysfunction and atherosclerosis in ApoE-/- diabetic mice." (PMID 38203413, 2023). "In conclusion, 3,4-DC reduces vascular injury in a second mouse model of atherosclerosis induced by HFD in ApoE−/− mice." (PMID 37989732, 2023). "To evaluate the overall m6A modification in atherosclerosis (AS), we first analyzed the total m6A level in the aorta of ApoE−/− mice that were fed with high-fat diet (HFD) for 26 weeks." (PMID 38097926, 2023).